RN7SL221P (RNA, 7SL, cytoplasmic 221, pseudogene)
Gene: Miscellaneous RNA gene on chromosome 6 (5,918,564 to 5,918,844, reverse strand). Ensembl gene ENSG00000239472.
Homologues: Orthologues: chimpanzee Metazoa_SRP (99% identical), macaque Metazoa_SRP (93% identical). Paralogues in human: RN7SL1 (81% identical), RN7SL3 (80% identical), RN7SL45P (80% identical), RN7SL2 (80% identical), RN7SL296P (80% identical), RN7SL448P (79% identical), RN7SL680P (79% identical), RN7SL408P (79% identical), RN7SL441P (78% identical), RN7SL7P (78% identical), RN7SL18P (78% identical), RN7SL220P (78% identical), and 703 more.